APOE (apolipoprotein E)
Diseases named in the same sentence as APOE in open-access papers (continued):
Sharing a sentence is not in itself a finding about the gene and the disease.
dementia (continued). "With the present study we provide epidemiological evidence that ApoE genotypes do not play a systematic role in the development of BBB dysfunction in a large group of patients with different types of dementia." (PMID 24386372, 2013). "We did not perform APOE genotyping here because it is not currently recommended in the diagnosis of AD or other forms of dementia." (PMID 23937917, 2013). "Since there is clear evidence for the role of ApoE in the pathogenesis of AD, it cannot be excluded that BBB dysfunction mediated by ApoE plays a role in the development of cognitive dysfunction in AD and other forms of dementia." (PMID 24386372, 2013). "Both APOE and ACE variants also affect behavior and the modification of behavioral changes (mood and anxiety) in dementia after nonpsychotropic pharmacological treatment." (PMID 22482072, 2012). "(x) APOE may also interact with PSEN1, ACE, A2M, and other genes to regulate the effect of drugs on cognition and behavioral changes in dementia." (PMID 22482072, 2012). "The prevalence of dementia was more than double in APOE carriers compared to that in non-carriers (adjusted PR = 2.58, 95%CI 2.06-3.22)." (PMID 21435264, 2011). "Individuals with dementia had a higher frequency of APOE ε4 compared with non-demented individuals in Japanese-American men." (PMID 21194415, 2010). "(i) CSF BDNF decreased across the human life-span in the absence of dementia or MCI and was independent of inheritance of Met-BDNF or the APOE ε4 allele." (PMID 19412541, 2009). "Given its epidemiological significance and its widespread use as a screening tool for early cognitive decline, we also extended our previous analysis to examine the effect of APOE *E4 on the Mini-Mental State Examination, MMSE, a brief screening test for dementia." (PMID 18620605, 2008). "The levels of CSF apoE were not significantly different between subjects who were cognitively normal who had a clinical dementia rating (CDR) score of 0 and those who had very mild (CDR 0.5) or mild-moderate dementia believed to be due to AD (CDR 1+)." (PMID 17430597, 2007). "A key next step is to test whether APOE-ε4 carriers are disproportionately likely to develop new dementia after a delirium episode, even in the absence of previous cognitive impairment." (PMID 41286463, 2026). "These insights together with our observations strengthen the hypothesis that APOE ε4 influences NPS through its role in neuroinflammation, opening avenues for future research into inflammation-targeted therapies for managing NPS in dementia." (PMID 39974048, 2025). "In ApoE genotyped participants (81%), females in the highest BPV tertile lacking the ɛ4 allele had increased risk of dementia (HR = 1.39; 1.04–1.84), while risk of cognitive decline was increased in both sexes lacking the ɛ4 allele (males HR = 1.25; 1.09–1.43; females HR = 1.14; 1.01–1.29)." (PMID 41109864, 2025). "APOE ε4 carriers may be particularly susceptible to low dream recall and future dementia given their higher global Aβ burden and DMN tau levels and the potential for APOE ε4 to influence the DMN via non-amyloid pathways." (PMID 41001478, 2025). "When examining the combined group of individuals with aMCI or dementia due to AD compared to cognitively unimpaired individuals, KL-VSHET carriers showed 41% lower odds of being classified within the cognitively impaired group (p = .205), with a stronger trend within APOE ε4 carriers." (PMID 41163083, 2025). "Second, we had no biomarker-confirmed diagnosis of dementia etiology in participants who developed dementia during follow-up, and the importance of various APOE-related pathways may differ between dementia subtypes." (PMID 40344552, 2025). "The non‐APOE PRS we developed was based on GWAS on AD, rather than all‐cause dementia or VaD." (PMID 38984680, 2024).
dementia (continued). "Finally, Cluster 3 appears to be a lower risk group for the development of dementia due to AD, defined mainly by rare (perhaps protective) variants in APP and almost no APOE ε4 individuals." (PMID 38693203, 2024). "Notably, in 2018, Wang and colleagues published results of a comparison of SNAP-25 levels in the CSF of patients with MCI, dementia, mild AD, and normal cognition, in carriers and non-carriers of APOE ε4." (PMID 39000060, 2024). "The presence of APOE ε4 did not affect age at onset of dementia." (PMID 39233587, 2024). "Together these findings suggest that an EPA-dominant formula may provide some benefit in APOE*E4 carriers with no dementia and WMLs, and DHA-dominant formulas may benefit noncarriers of APOE*E4 with mild-to-moderate AD." (PMID 39088212, 2024). "Furthermore, NECTIN2 gene is located in a major dementia locus along with TOMM40 and APOE genes." (PMID 38408961, 2024). "However, more research is needed to align APOE-genetic disclosure protocols within a research setting for cognitively normal adults without first degree relatives with dementia." (PMID 38167083, 2024). "Further, approximately 80% of APOE ε4 carriers did not develop dementia during the long follow‐up." (PMID 39023302, 2024). "However, when using Aβ PET+ subgroups, dementia progression was accelerated considerably in the Sleep+ group regardless of APOE genotype (+/−)." (PMID 38421124, 2024). "A recent study illustrated that the association between White Matter Hyperintensity(WMH) and grey matter loss is more pronounced in Apolipoprotein E ε4(APOE-ε4) non-carriers than APOE-ε4 carriers in the cognitively unimpaired(CU) and early-stage dementia populations." (PMID 39044522, 2024). "Finally, neither of the personality factors (CE nor TL) significantly predicted the conversion to AD-type dementia in the Cox regression models adjusted for age, sex, education level and APOE-ε4 carriership." (PMID 38450380, 2024). "The objective of this review is to present the current evidence on APOE as a non-protagonist actor not just in the pathogenesis of major neurodegenerative diseases, such AD and dementia, but in the outcome and stratification of patients with PD, HD, acquired brain injury, coma, and DoC." (PMID 39596597, 2024). "However, a few studies have not found significant interactions between APOE ε4 and age, sex, or education in relation to cognitive function and dementia." (PMID 38889280, 2024). "We did not observe greater dementia risk for APOE4+ compared to APOE3 carriers in relation to 24‐OHC/27‐OHC ratio, which also raises questions and further necessitates examination in larger samples to clarify APOE‐oxysterol relationships." (PMID 38574442, 2024). "However, other studies did not support the role of APOE in differentiating men and women when progressing to dementia." (PMID 38539590, 2024). "Adding potential confounders including traffic-related particulate matter, smoking status, chronic diseases, and apolipoprotein E status to the multivariable model, or removing cases with dementia onset within the first year of follow-up did not substantially alter the results." (PMID 39580439, 2024). "Second, although we had to rely on publicized certifications to distinguish individual clinicians’ expertise, clinicians with a certification in the specific expertise areas related to dementia treatment may not always be familiar with APOE testing." (PMID 38225507, 2024). "However, except for a convenience sample study that reported an APOE candidate gene in East Africa,65to the best of our knowledge, there is no population-based genetics or epigenetics research on dementia and cognitive impairment in East Africa." (PMID 38995792, 2024). "The current study provides the first evidence in an exclusively older-age sample with narrow age-range that baseline and change in plasma p-tau181/NfL are associated with subsequent cognitive decline between 72 and 82 years, beyond APOE status and in the absence of dementia." (PMID 37180996, 2023).
dementia (continued). "Rather surprisingly, analysis in men restricted to non‐APOE ε4 or non‐APOE ε2 carriers suggested a protective association of elevated TC, LDL‐C, non‐HDL‐C (and ApoB for non‐APOE ε2 carriers) with dementia but this was not the case for mortality or CHD, where results were in the expected direction." (PMID 37243914, 2023). "Age of clinical onset of the MCI and dementia converters did not significantly differ between APOE e2+ and e2− genotypes, but the trends were in the hypothesized direction such that APOE e2+ mutation carriers had on average later clinical onset." (PMID 37612284, 2023). "However, previous research has not directly outlined the modulation of APOE on the trajectory of cerebral atrophy with aging during the conversion from cognitive normal (CN) to dementia (CN2D)." (PMID 37323144, 2023). "We started by targeting five brain regions from one healthy aged donor (90-year-old male without dementia, APOE ε3/ε3, and a post-mortem interval of 3.4 hours), including the hippocampus (HIP), cerebellum, substantia nigra (SN), caudate nucleus, and middle frontal gyrus (MFG) (left)." (PMID 37398389, 2023). "The knowledge gained from previous studies makes us to speculate three assumptions about APOE ɛ2 and APOE ɛ4, meanwhile, rs-fMRI and structure MRI studies of these two genotypes have not been reported, especially in non-dementia elderly." (PMID 37636817, 2023). "Whole plasma ApoE concentration at baseline was determined in 3031 participants, of which 2893 were European Americans (EAs), including 2412 who remained non-demented (ND) and 481 with incident dementia (91.4% AD dementia)." (PMID 37666928, 2023). "Therefore, we believe that elevated plasmatic APOE levels and BBB damage could favour the early development of dementia." (PMID 37175748, 2023). "However, measuring the cerebrospinal fluid/plasma albumin ratio an indicator of BBB permeability, Janelidze and Colleagues reported that the ratio was increased in all dementias compared with controls, but is not related to APOE genotype." (PMID 37467176, 2023). "However, no study has directly outlined the modulation of APOE on the trajectory of cerebral atrophy through the whole process from normal cognition to dementia." (PMID 37323144, 2023). "Our results indicate that the AD PRS does not drive PD dementia, suggesting that APOE e4 may drive dementia in PD cases by an AD pathology-independent mechanism." (PMID 37987016, 2023). "However, no study has paid attention to the effect of APOE on the trajectory of cerebral atrophy through the whole process from normal cognition to dementia." (PMID 37323144, 2023). "Of these participants, 3038 (67% of participants who had APOE genotype data) received a diagnosis of a cataract before dementia onset or the end of the study, did not have surgery before the ACT study baseline, and had 1 or more study visits after cataract diagnosis." (PMID 34870676, 2022). "However, the main objective was to explore the neural underpinnings to previous behavioral findings, where individuals with a positive family history of dementia and APOE e4 carriers demonstrated performance deficits on non-standard visuomotor tasks." (PMID 36711200, 2022). "Last, despite the use of one of the largest well‐phenotyped imaging cohort studies in old age and dementia, we had limited power to study genotypic vulnerability, which may explain the lack of observed APOE Ɛ4 moderator effects." (PMID 35129272, 2022). "Interestingly, a recent study reported that ApoE-HDL lacking ApoC-III was associated with better cognitive function and lower dementia risk." (PMID 35389891, 2022). "Comparison of APOE variants in MSA patients with and without dementia." (PMID 36508411, 2022).
dementia (continued). "Further, APOE ε4 homozygosity among cognitively normal participants is associated with earlier and more abundant Aβ deposition, earlier pre-clinical memory decline, and an increased incidence of conversion to dementia, in comparison to APOE ε4 heterozygotes and noncarriers." (PMID 35617280, 2022). "Donepezil treatment is not recommended in BCHE-K and APOE-4 carriers with MCI or dementia." (PMID 35330211, 2022). "Additionally, DM was found to be associated with alteration only in CSF total tau level, but not in p-tau or Aβ in ApoE E4 carriers diagnosed with MCI or early dementia." (PMID 35682821, 2022). "Additionally, myelination in the elderly without dementia, measured through MWF, has been associated with episodic and semantic memory capacity and the AD risk allele apolipoprotein E (APOE) ε4." (PMID 36284351, 2022). "However, in people between 39 and 90 years of age, serum and CSF levels of α-klotho are positively correlated and predict scores on both the Mini-Mental State Examination test and the Clinical Dementia Rating regardless of sex or APOE genotype." (PMID 35884888, 2022). "A possible interpretation is that APOE-ε4 carriers may have already accumulated sufficient AD pathology to manifest dementia symptoms earlier than noncarriers." (PMID 34228116, 2021). "The lack of strong evidence and the existing differences could be explained genetically, as the APOE ε4 genotype impacts differently on the relevance of hypercholesterolaemia in dementia compared to APOE ε4 non-carriers." (PMID 34639242, 2021). "Three out of the four APOE ε4 non-carriers among these subjects had both AD and dementia." (PMID 33637690, 2021). "Interestingly, the associations between APOE/AD PRS and Aβ misfolding were not evident in participants without dementia diagnoses, possibly because those at high genetic risk of AD experience Aβ misfolding earlier and, therefore, also a diagnosis earlier." (PMID 33934115, 2021). "This may suggest that higher education may be critical for individuals with an APOE e4 gene and a parental history of dementia, compared to individuals without that fall outside the high-risk group." (PMID 34124650, 2021). "In summary, we demonstrated that PRS could predict conversion of MCI to dementia, showing a significant interaction between PRS and APOE ε4 carrier status, particularly stronger association in APOE ε4 non-carriers than in carriers." (PMID 34465370, 2021). "Additionally, we did not adjust for apolipoprotein E (APOE)-polymorphism, a major risk factor for dementia." (PMID 34852818, 2021). "In the present study we examined the hypothesis that high consumption of meat increases the incidence of dementia in the general population, which may be more pronounced among APOE ε4 noncarriers." (PMID 33748832, 2021). "The significant differences between APOE4+ and APOE4- are identified within the left hemispheric DMN and in the whole brain DMN in two datasets, providing evidence that the APOE e4 genotype leads to distinct alterations of functional DMN several years before the occurrence of dementia symptoms." (PMID 32733231, 2020). "However, the experimental data on the interaction between IAPP and ApoE are very scarce in spite of the apparent importance of ApoE in IAPP-related pathologies and the crosslink between IAPP pathologies and AD as well as other types of dementia." (PMID 31947546, 2020). "Although people who have already been diagnosed with AD have been included and those with other types of dementia have been excluded, inclusion bias may have existed because neuroimaging or apolipoprotein E genotypes were not assessed for all participants." (PMID 33202663, 2020). "Importantly, the research cohort imaged in this study mainly comprised cognitively unimpaired MS patients, in contrast to the case series described here, all of whom had dementia (and in whom ApoE status was not tested)." (PMID 32556533, 2020).
dementia (continued). "APOE ε4 carriers who survive and do not develop dementia until after the age of 75 to 80 years represent a highly selected group where other genetic and/or non‐genetic risk and protective factors may also be important." (PMID 31736136, 2020). "Therefore, the effects of APOE ε4 on ongoing cognitive deterioration or development of dementia have not yet been reported in patients with CADASIL." (PMID 33328970, 2020). "One DS participant (D4, 39 years old) with TREM2 R47H (T allele) who was heterozygous for ApoE (ɛ3/ɛ4) slowly deteriorated and developed dementia, whereas another DS participant (D7, 37 years old) who was homozygous for ApoE (ɛ3/ɛ3) but had no clinical symptoms of dementia as yet." (PMID 30909239, 2019). "This study did not assess APOE genotype or tau haplotype, which may vary with AD and tangle-predominant dementia." (PMID 31806014, 2019). "However, D7 (37 years old) was homozygous for ApoE (ɛ3/ɛ3) and still has no clinical symptoms of dementia yet." (PMID 30909239, 2019). "Moreover, previous and more recent investigations began showing that in the context of non-AD dementias such as FTD or cognitive decline in ALS, the modifying action of APOE polymorphism can be rather different from what is observed in classical AD." (PMID 30677746, 2019). "In addition, the difference in dementia conversion rates for those with and without APOE ε4 (regardless of age beliefs) was 2.14%." (PMID 29414991, 2018). "Though an opposite link was observed between Aβ1–42 and increased dementia risk in APOE-ε4 noncarriers, the similarity in the direction of effect estimates further suggests a role of mixed pathology in the development of dementia, regardless of APOE carrier status." (PMID 29960604, 2018). "Out of 11 epidemiological reports published between 2005 and 2015, only two accounted for ApoE genotype, with one finding an additive effect of ApoE4 genotype and head injury in the risk of developing dementia, and the other reporting little evidence for a relationship between ApoE4 and dementia." (PMID 30249283, 2018). "Importantly, if a combination of subjective complaints and biomarkers is desired to be included in routine screening for dementia, the reality is that information about β-amyloid and APOE status is not always available in clinical settings." (PMID 28287184, 2017). "Lifetime incidence rose consistently with APOE-e4 dose: for MCI/dementia, it ranged from 11.94%–15.57% for those with no copies of APOE-e4 to 37.47%–46.66% for APOE-e4/e4 homozygote individuals; for dementia alone, it ranged from 5.26%–6.83% for no copies to 30.76%–40.26 for homozygote individuals." (PMID 28323826, 2017). "Some epidemiological data suggest that physical activity is more protective in APOE ε4 carriers compared to non-carriers with respect to incidence of dementia; cerebral amyloid deposition; cognitive function; cognitive decline and memory-related brain activation." (PMID 28327083, 2017). "For the majority of the population—those without the APOE ε4 gene—PA may have protective effects against the development of dementia." (PMID 28230730, 2017). "Univariate analysis demonstrated significant differences between the group with probable dementia and the group without dementia for the following variables: positive APOE ɛ4 carrier status (p < 0.001), lower BMI at age 79 (p = 0.026) and current smoking status at age 79 (p = 0.039)." (PMID 28578665, 2017). "There was no family history of dementia, and her ApoE genotype was 3/3." (PMID 26870879, 2016). "The study found no increasedrisk of dementia due to TBI in the absence of APOE ε4." (PMID 29213985, 2015). "Thus, we cannot rule out the possibility that the effect of APOE was, at least in part, due to dementia-related brain changes." (PMID 26252210, 2015). "One factor that may contribute to the effect of APOE on PS in elderly persons without dementia is microstructural white matter integrity." (PMID 26252210, 2015).